GADD45B (growth arrest and DNA damage inducible beta)
Diseases named in the same sentence as GADD45B in open-access papers (continued):
Sharing a sentence is not in itself a finding about the gene and the disease.
Cerebral ischemia (4 papers, 2015 to 2023). Restriction of arterial blood supply to the brain associated with insufficient oxygenation to support the metabolic requirements of the tissue. "Reduced GADD45B expression induced depression-like behaviors after cerebral ischemia by releasing pro-inflammatory cytokines." (PMID 37511062, 2023). "In this study, Gadd45b was shown to protect against rat brain ischemia injury by inhibiting apoptosis." (PMID 36311022, 2022). "Our results suggested that the ALK5 signaling pathway plays a critical role in mediating neural plasticity and neurological function recovery via Gadd45b after cerebral ischemia, representing a new potential target for cerebral I/R injury." (PMID 31043581, 2019). "Recently, our study has reported that rat brain ischemia stimulated the expression of Gadd45b in the cortex, Gadd45b-RNAi significantly decreased the level of BDNF and inhibited axonal plasticity after MCAO." (PMID 26698301, 2015). "In addition, several newly published preclinical studies demonstrate that Gadd45b protects against cerebral ischemia damage in both transitory localized and global models of cerebral ischemia." (PMID 36311022, 2022). "In addition, Gadd45b expression is dramatically increased in hippocampal CA1 neurons from rats with transient global cerebral ischemia." (PMID 36311022, 2022). "Studies of growth arrest and DNA damage-inducible beta (Gadd45b) in cerebral ischemia." (PMID 36311022, 2022). "Here, we hypothesized that ALK5 signaling regulates neural plasticity and neurological function recovery after cerebral ischemia/reperfusion (I/R) via Gadd45b." (PMID 31043581, 2019). "However, little is known about the molecular mechanisms for how the expression of Gadd45b is regulated in brain ischemia." (PMID 26698301, 2015). "However, little is known of the molecular mechanisms of how Gadd45b expression regulated and the down-stream targets in brain ischemia." (PMID 26698301, 2015). "This indicated that transient action of Gadd45b may lead to the lasting affect after brain ischemia." (PMID 26698301, 2015). "And Gadd45b maybe affect the level of BDNF by demethylation of CpG islands in brain ischemia." (PMID 26698301, 2015). "Based on these studies, given that the expression of Gadd45b is affected by UPS, we hypothesize that Huwe1 might play an important role in regulating Gadd45b expression in brain ischemia." (PMID 26698301, 2015).
diabetes (4 papers, 2016 to 2024). "The decrease of Gadd45β expression and increase of lipid uptake were also observed in mice with obesity or diabetes." (PMID 39653679, 2024). "Here, using an RNA sequencing approach, we determined that GADD45B was significantly upregulated in diabetic kidneys, which was accompanied by renal tubular epithelial-mesenchymal transition (EMT) and apoptosis, as well as elevated MAPK pathway activation." (PMID 33013461, 2020). "Here, we show that “growth arrest and DNA damage‐inducible” GADD45β as a dysregulated gene transcript during fasting in several models of metabolic dysfunction including ageing, obesity/pre‐diabetes and type 2 diabetes, in both mice and humans." (PMID 27137487, 2016). "Furthermore, fasting induces Gadd45β expression in the liver, correlating with alterations in lipid metabolism and implications for diabetes." (PMID 39653679, 2024). "Liver Gadd45β expression was upregulated in several mouse models of obesity and diabetes." (PMID 39653679, 2024). "Through liver‐specific GADD45β manipulation in vivo, we demonstrated that the altered liver fatty acid metabolism in obesity/diabetes and ageing might result from altered liver GADD45β expression, particularly during the fasted state." (PMID 27137487, 2016). "Furthermore, in mouse and human metabolic dysfunction such as type 2 diabetes, obesity/pre‐diabetes and the aged, liver GADD45β expression is dysregulated thereby contributing to aberrant lipid/glucose homoeostasis." (PMID 27137487, 2016). "The relationship between CAR and Gadd45β in lipid metabolism or diabetes has been confirmed by a study on high‐fat diet mice, in which CAR activation has the effect of anti‐diabetes, reducing fat and improving IR." (PMID 39653679, 2024). "In the present study, we aimed to investigate the effect of GADD45B on renal tubular EMT and apoptosis in the context of diabetes and to further explore whether the MAPK pathway is involved in this regulation process." (PMID 33013461, 2020).
esophageal cancer (4 papers, 2005 to 2025). A primary or metastatic malignant neoplasm involving the esophagus. "Decreased GADD45B gene expression levels have been described in several human tumors, such as lymphoma, thyroid, breast, cervical, lung, and esophageal cancers, often by epigenetic regulation." (PMID 32425887, 2020). "Through transfection of siRNAs specific for MAP2K3 and GADD45B, as well as plasmids harboring full-length human MAP2K3 and GADD45B sequences, we found MAP2K3 and GADD45B inhibited esophageal cancer cell proliferation." (PMID 32873775, 2020). "Microarray results showed the influence of SFE on esophageal cancer cells was related with stearoyl-CoA desaturase (SCD), cadherin 3 (CDH3), mitogen-activated protein kinase kinase 3 (MAP2K3) and growth arrest and DNA damage inducible beta (GADD45B)." (PMID 32873775, 2020).
Parkinson disease (4 papers, 2022 to 2025). A progressive degenerative disorder of the central nervous system characterized by loss of dopamine producing neurons in the substantia nigra and the presence of Lewy bodies in the substantia nigra and locus coeruleus. "GADD45β has also been implicated in the pathogenesis of Parkinson’s disease." (PMID 40083548, 2025). "Previous studies showed that in a 6-hydroxydopamine (6-OHDA) induced Parkinson’s mouse model, GADD45β expression was lower in the dorsal striatum." (PMID 40083548, 2025). "Finally, a new role for GADD45B in the pathogenesis of Parkinson’s disease is provided by studies both in vivo and in vitro." (PMID 35163690, 2022). "However, Gadd45b could be a potential target in countering dopamine precursor 3,4-dihydroxyphenyl-L-alanine (L-DOPA)-induced dyskinesia (LID) Parkinson’s disease." (PMID 36311022, 2022).
psychosis (4 papers, 2019 to 2023). "Multiple investigations over the last decade have identified Gadd45b in the pathogenesis of psychosis of the major psychosis." (PMID 36311022, 2022). "GADD45β has been shown to regulate activity-dependent DNA demethylation at specific loci in genes like BDNF and fibroblast growth factor 1 (Fgf1) that have been implicated in neurogenesis, synaptic plasticity, and psychosis." (PMID 36781843, 2023). "Gadd45b appears to control methylation and upregulate reelin, GAD67, and BDNF expression in the brains of individuals with psychosis." (PMID 36311022, 2022).
schizophrenia (4 papers, 2022 to 2024). A major psychotic disorder characterized by abnormalities in the perception or expression of reality. "GADD45b has been proposed as a hub gene differentially expressed in previous bioinformatic studies analyzing microarray datasets from patients with schizophrenia." (PMID 39727940, 2024). "In order to further explore the diagnostic value of the four hub genes (NFKBIA, CDKN1A, BTG2, and GADD45B) for schizophrenia, this experiment used ROC curves for evaluation." (PMID 35741729, 2022). "In conclusion, NFKBIA, CDKN1A, BTG2, GADD45B, and the joint indicators of four hub genes have great potential as biomarkers and therapeutic targets for the diagnosis of schizophrenia." (PMID 35741729, 2022). "The abnormal activation of GADD45B in the nervous tissue of schizophrenia is consistent with the high expression of GADD45B in the patient group in this study." (PMID 35741729, 2022). "GADD45b up-regulation was detected in some of the datasets of schizophrenia analyzed in our study." (PMID 39727940, 2024). "Based on bioinformatics methods, this is the first study that found four hub genes closely related to schizophrenia (NFKBIA, CDKN1A, BTG2, and GADD45B)." (PMID 35741729, 2022).
asthma (3 papers, 2020). "Recent biomarker identification study indicated GADD45B in their list of genes that can be targeted in chronic diseases like asthma, IPF, and COPD." (PMID 33013423, 2020). "They include RBM42, STX5, and TRIM41 in asthma, CYP27A1, GM2A, LGALS9, SPI1, and NLRC4 in COPD, as well as ATF3, PPP1R15A, ZFP36, SOCS3, NAMPT, and GADD45B in IPF." (PMID 31952466, 2020). "These genes included RBM42, STX5, and TRIM41 in asthma, CYP27A1, GM2A, LGALS9, SPI1, and NLRC4 in COPD, ATF3, PPP1R15A, ZFP36, SOCS3, NAMPT, and GADD45B in IPF, LRRC48 and CETN2 in asthma-COPD, COL15A1, GIMAP6, and JAM2 in asthma-IPF and LMO7, TSPAN13, LAMA3, and ANXA3 in COPD-IPF." (PMID 31952466, 2020).
autoimmune disease (3 papers, 2018 to 2025). A disorder resulting from loss of function or tissue destruction of an organ or multiple organs, arising from humoral or cellular immune responses of the individual to their own tissue constituents. "Additionally, myasthenia gravis (MG) is an autoimmune disease caused by dysfunctional neuromuscular junction transmission, and Gadd45b expression is downregulated in patients with thymoma presenting with myasthenia gravis." (PMID 36311022, 2022). "Why does the same isoform of GADD45β have different roles in the same autoimmune disease?" (PMID 40083548, 2025). "Experimental studies have indicated that some autoimmune diseases are closely related to Gadd45b." (PMID 36311022, 2022).
colitis (3 papers, 2019 to 2025). Inflammation of the colon. "Gadd45β plays a protective role by regulating TGF-β signaling to promote epithelial repair, and Gadd45β-deficient mice exhibit markedly increased susceptibility to DSS-induced colitis and mortality." (PMID 40977735, 2025). "Gadd45β-KO mice exhibited drastically greater susceptibility to dextran sulfate sodium (DSS)-induced colitis and mortality than C57BL/6J mice." (PMID 31666502, 2019). "Under these conditions, Gadd45β-KO mice developed more severe colitis than WT mice, as evidenced by the development of key clinical features of colitis (mortality, body weight loss, bloody diarrhea, and hematocrit changes)." (PMID 31666502, 2019). "We assessed whether Gadd45β is involved in UC by using a mouse model of DSS-induced colitis, a well-defined chemical-induced model of colitis resembling human UC32." (PMID 31666502, 2019). "This study shows a multifaceted role for Gadd45β in DSS-induced colitis." (PMID 31666502, 2019). "However, the roles of Gadd45β in immune cells during colitis remain unknown and must be further studied in the future." (PMID 31666502, 2019). "However, the cellular mechanism by which Gadd45β mediates DSS-induced colitis is unclear." (PMID 31666502, 2019). "Gadd45β was strongly expressed in the small and large intestine and protected against DSS-induced colitis." (PMID 31666502, 2019). "In DSS-induced colitis, STAT3 phosphorylation was significantly increased in the colon tissue of Gadd45β-KO mice compared to that of WT mice, while active PKB phosphorylation in colon tissue was not altered by Gadd45β." (PMID 31666502, 2019). "In this study, we investigated the role of Gadd45β in intestinal homeostasis using rodents lacking Gadd45β and control wild-type (WT) C57BL/6J mice to establish a dextran sulfate sodium (DSS)-induced colitis model mimicking the clinical pathogenesis of UC." (PMID 31666502, 2019).
COVID-19 (3 papers, 2023 to 2024). A disease caused by infection with severe acute respiratory syndrome coronavirus 2. "The protein–protein interaction (PPI) network of DEGs was then constructed and six genes named RAD51, ALDH1A1, UBA52, CUL3, GADD45B, and CDKN1A were identified as the commonly dysregulated hub genes among HFRS and COVID-19." (PMID 37234545, 2023). "Our study uncovered six genes named RAD51, ALDH1A1, UBA52, CUL3, GADD45B, and CDKN1A were found to be commonly dysregulated among HFRS and COVID-19." (PMID 37234545, 2023).
cutaneous melanoma (3 papers, 2019 to 2025). A primary melanoma arising from atypical melanocytes in the skin. "Information of 11 types GADD45B methylation in skin melanoma." (PMID 31681565, 2019). "Therefore, we hypothesized that GADD45B overexpression could inhibit the proliferation and promote the apoptosis of cutaneous melanoma cells; however, further experiments are needed to verify this effect." (PMID 40350499, 2025). "After KD of MAGOH and MAGOHB using the siMAGOH/B Pool, a significant increase in GADD45A mRNA expression was observed in the cutaneous melanoma cell lines Mel Ho and 501Mel, whereas no obvious changes in the expression of GADD45B or GADD45G could be detected." (PMID 36497117, 2022).
experimental autoimmune encephalomyelitis (3 papers, 2018 to 2025). An autoimmune demyelinating disease of the central nervous system that is produced experimentally in animals by the injection of homogenized brain or spinal cord in Freund's adjuvant. "Moreover, GADD45b-deficient mice showed exacerbated experimental autoimmune encephalomyelitis, while GADD45b and GADD45g double-deficient mice develop a spontaneous lymphoproliferative disease." (PMID 34272424, 2021). "GADD45B is involved in Th1-response, and transgenic mice with a knockout of GADD45B develop a severe form of experimental autoimmune encephalomyelitis." (PMID 30308012, 2018). "However, K/BxN serum-induced arthritis and experimental autoimmune encephalomyelitis (EAE) were alleviated by GADD45β, suggesting that GADD45β plays a complex role in regulating adaptive immunity and can enhance or suppress inflammation according to different disease models." (PMID 40083548, 2025).
gastric cancer (3 papers, 2023 to 2025). A primary or metastatic malignant neoplasm involving the stomach. "Furthermore, GADD45B promotes immunosuppression within the tumor microenvironment by modulating signaling interactions between gastric cancer cells and tumor-associated fibroblasts, vascular endothelial cells, and other microenvironmental cells." (PMID 37608794, 2023). "During the carcinogenic phase of chronic atrophic gastritis, GADD45B primarily inhibits gastric cancer development by suppressing the WNT signaling pathway." (PMID 37608794, 2023). "In summary, GADD45B exerted a significant influence on the metabolic pathways of gastric cancer cells." (PMID 37608794, 2023). "GADD45B acts as a tumor suppressor during the progression from chronic atrophic gastritis to gastric cancer by inhibiting the WNT signaling pathway." (PMID 37608794, 2023). "Moreover, GADD45B plays a crucial role in mediating the communication between gastric cancer cells and the immune microenvironment, resulting in enhanced invasiveness and poor prognosis for GC patients." (PMID 37608794, 2023). "However, in advanced gastric cancer tissues, GADD45B exhibits a positive correlation with WNT signaling intensity, indicating its involvement in tumor progression." (PMID 37608794, 2023). "We found that GADD45B plays distinct roles in different stages of gastric cancer." (PMID 37608794, 2023). "Moreover, GADD45B expression was found to potentially influence the efficacy of chemotherapy in stomach cancer patients." (PMID 37608794, 2023). "Additionally, GADD45B exerted broad regulatory effects on the metabolic pathways involved in chronic atrophic gastritis and gastric cancer tissues, ultimately facilitating the progression of gastric cancer." (PMID 37608794, 2023).
glomerular diseases (3 papers, 2016 to 2023). "Similar to GADD45A, GADD45B expression was increased in various glomerular diseases, such as IgA nephropathy and diabetic kidney disease." (PMID 37511062, 2023). "Taken together, our findings demonstrated that triptolide attenuated proteinuria and podocyte apoptosis via inhibition of NF-κB/GADD45B signalling, which provides a new understanding of the antiproteinuric effects of triptolide in glomerular diseases." (PMID 30022148, 2018). "Taken together, our findings demonstrated that GADD45B has an important role in podocyte injury and may be a therapeutic target for the management of podocyte injury in glomerular diseases." (PMID 26794661, 2016).
Insulin resistance (3 papers, 2016 to 2025). Increased resistance towards insulin, that is, diminished effectiveness of insulin in reducing blood glucose levels. "While there were no substantial effects of GADD45β loss on biometric parameters (Fig EV3I–K), similar to the whole‐body KO study, hepatocyte‐specific GADD45β silencing worsened the progression of insulin resistance upon high‐fat diet‐induced obesity." (PMID 27137487, 2016). "Consistent with a key role for FABP1 localisation in explaining the altered FA metabolism modulated by GADD45β expression, FABP1 is a highly abundant protein in the liver which has a role in cellular uptake of FAs and affects the development of insulin resistance in obesity." (PMID 27137487, 2016).
Papillary Thyroid Carcinoma (3 papers, 2020 to 2023). "Elevated expression of GADD45B has also been identified as a prognostic factor for papillary thyroid cancer patients who have undergone complete thyroidectomy and radioactive iodine therapy, showing reduced disease-free survival." (PMID 37608794, 2023).
pituitary adenomas (3 papers, 2014 to 2025). "GADD45B was displayed to be downregulated in pituitary adenomas (-68-fold) through microarray data, subsequently verified by qPCR and immunoblotting, and in vitro experiments identified its role as a tumor suppressor." (PMID 25642247, 2015). "It is well acknowledged that the overexpression of GADD45β may inhibit tumor growth through activating apoptosis-inhibiting factors, which indicates that GADD45β may also serve a potential inhibitor of pituitary adenoma." (PMID 25360166, 2014).
Sepsis (3 papers, 2007 to 2019). Sepsis is defined as life-threatening organ dysfunction caused by a dysregulated host response to infection. "We recently reported that the release of proinflammatory cytokines into the blood was decreased in Gadd45β-KO mice but increased in the lungs in experimental sepsis models." (PMID 31666502, 2019). "In an experimental sepsis model, Gadd45β-KO mice exhibited reduced myeloid cell recruitment to the peritoneal cavity upon LPS stimulation." (PMID 31666502, 2019). "While IL6 was previously identified as biomarker for sepsis, GADD45B, SOCS3, and IRG1 were shown to be up-regulated in septic patients." (PMID 25814982, 2015). "With regard to apoptosis, both pro-apoptotic (COP1, GADD45B and RIPK2) and anti-apoptotic (TNFAIP3 and BIRC3) genes were induced in the early stages of sepsis." (PMID 17324256, 2007).